RN7SL344P (RNA, 7SL, cytoplasmic 344, pseudogene)
Gene: Miscellaneous RNA gene on chromosome 1 (211,792,111 to 211,792,406, reverse strand). Ensembl gene ENSG00000241395.
Homologues: Orthologues: chimpanzee Metazoa_SRP (99% identical), macaque Metazoa_SRP (94% identical). Paralogues in human: RN7SL1 (85% identical), RN7SL2 (84% identical), RN7SL3 (82% identical), RN7SL478P (82% identical), RN7SL709P (82% identical), RN7SL556P (82% identical), RN7SL655P (82% identical), RN7SL333P (81% identical), RN7SL604P (81% identical), RN7SL492P (81% identical), RN7SL543P (81% identical), RN7SL296P (81% identical), and 704 more.